STAT3 (signal transducer and activator of transcription 3)
Diseases named in the same sentence as STAT3 in open-access papers (continued):
Sharing a sentence is not in itself a finding about the gene and the disease.
glioma (continued). "It was shown that Stat3 and miR-21 closely interact, and the complex interplay between non-coding RNAs (including miR-21) and Stat3 related to its function in glioma has recently been thoroughly reviewed." (PMID 35572197, 2022). "It was reported that glioma initiating CD133(+) cells and Mφs/microglia cointeraction activated expression of B7-H4 via IL6-activated STAT3, thereby blocking effective T-cell immune responses within the microenvironment of gliomas." (PMID 36685508, 2022). "The deregulation and constant activation of STAT3 in gliomas is considered to result from an aberrant signal from upstream regulators, since no gain-of-function mutation of this molecule has been identified yet." (PMID 35409080, 2022). "Previous studies reported that Stat3 was up-regulated in rat MSCs after co-cultured with glioma cells." (PMID 36295083, 2022). "Preclinical and clinical investigations showed that IL6-JAK-STAT3 pathway inhibition has therapeutic benefits in cancer and that STAT3 inhibition inhibits the growth of glioma cells." (PMID 36105094, 2022). "For instance, miR-124 can promote T cell-mediated immune clearance of glioma by suppressing signal transducer and activator of transcription 3 (STAT3) signaling." (PMID 35181676, 2022). "In summary, our data demonstrated that TGFBI was secreted by M2-like TAMs, promoting the maintenance of GSCs and glioma growth through integrin αvβ5-Src-Stat3 signaling." (PMID 35673564, 2022). "In tumor cells, blocking CSC signaling pathways, such as AKT and signal transducer and activator of transcription-3 (STAT-3), in glioma is an effective practical approach that needs further investigation for application in other solid tumors." (PMID 35205721, 2022). "In order to determine the interaction between NEDD4L and STAT3 in glioma cells, we engineered glioma U251 cells to overexpress NEDD4L, which was validated by both qPCR and western blot." (PMID 36618071, 2022). "Consistent with this, studies have demonstrated that tumour progression in glioma is driven by an increase in proliferation and migration, and MSCs increase proliferation and maintain stemness in glioma via the IL‐6/gp130/STAT3 pathway." (PMID 35908277, 2022). "Here, we identified LMO2 as a cytoplasmic activator for signal transducer and activator of transcription 3 (STAT3) signaling in glioma stem cells (GSCs) through biochemical and bioinformatics analyses." (PMID 35805116, 2022). "Meanwhile, in CNS pathologies, as in gliomas, this cytokine is positively regulated, contributing to the activation of the signal transducer and activator of the transcription 3 (STAT3) signaling pathway." (PMID 35057010, 2022). "It has been demonstrated that inhibition of STAT3 through various approaches can trigger growth arrest as well as apoptosis of glioma cells." (PMID 36618071, 2022). "CD163 expression induces Stat3 activation, and direct contact between macrophages and glioma cells induces strong CD163 expression in macrophages via Stat3 activation." (PMID 35132816, 2022). "STAT3 tyrosine phosphorylation has been proved to accelerate the growth and glioma cell proliferation ensuing in significant long‐term survival." (PMID 37786890, 2022). "miR-519a promotes chemosensitivity and enhances autophagy of glioma cells by regulating STAT3/Bcl2 signaling." (PMID 35432536, 2022). "Intratumoral CD68+ (P = 0.0029), CD11c+CD68+ (P = 0.0018) and CD11c+CD68+CD163+ (P = 0.0029) cells were more likely to express p-STAT3 in gliomas." (PMID 35316217, 2022). "Through the JAK/STAT3 pathway, IL-6 promotes B7-H4 expression in gliomas, whereas STAT3 modulates B7-H4 transcription by enhancing the B7-H4 promoter." (PMID 36499340, 2022). "As the cluster keyword, STAT3 and its related pathways like JAK2/STAT3 pathway are widely researched in gliomas." (PMID 36338770, 2022).
glioma (continued). "GSCs inhibited the maturation of DCs and the killing effects of T cells on glioma cells by decreasing miR-106a/20b levels and consequently regulating STAT3 expression." (PMID 36157880, 2022). "The phosphorylation of STAT3, especially at the tyrosin-705 site, was observed in the BEV-treated glioma specimens, and the additional blockage of STAT3 significantly reduced the tumor size." (PMID 35448036, 2022). "Hypoxic glioma-derived exosomes deliver miRNA-1246 to promote M2 macrophage polarization by regulating TERF2IP through STAT3 signaling." (PMID 35432536, 2022). "Immunohistochemical staining results of 125 brain tissue samples showed that the expression trends of ZDHHC4, p-GSK3β (Y216), and p-STAT3 (Y705) were consistent and positively correlated with the pathological grade of glioma." (PMID 35606353, 2022). "Immune response to the presence of glioma is known to be suppressed by tumor cell–secreted factors that activate the signal transducer and activator of transcription 3 (STAT3) pathway." (PMID 35316217, 2022). "Second, despite similar T cell frequencies in gliomas and brain metastases, glioma T cells preferentially interacted with CD68+p-STAT3– monocyte-derived cells within tumor relative to that observed for brain metastases (P = 0.023)." (PMID 35316217, 2022). "In summary, we found that exosomal miR-3591-3p can facilitate macrophage polarization toward the M2 phenotype by targeting CBLB to activate the JAK2/PI3K/Akt/mTOR and STAT3 pathways, which in turn promotes glioma progression." (PMID 36085418, 2022). "We found that ciglitazone had multiple actions on the glioma, including the inhibition of angiogenesis, migration, decreased STAT3 phosphorylation, arrest of the cell cycle, activation of proteasome and lysosome, and increased autophagy." (PMID 36362294, 2022). "By inhibiting phosphorylation of JAK2 and STAT3, which are highly activated in many malignant cells, including glioma cells, miR-33a inhibits the growth, invasion, and EMT of tumor cells." (PMID 36061185, 2022). "Exploring miRNAs with the ability to inhibit STAT3 gene expression would help in developing a reasonable glioma immunotherapy." (PMID 36157880, 2022). "Inhibition of JAK2 activity with AG490, WP1066, sorafenib, and WP1193 downregulated STAT3 activity, inhibited proliferation, migratory/ invasive behavior, and focal adhesion kinase signaling of glioma cell lines, and resulted in apoptosis." (PMID 33960104, 2022). "We first analyzed STAT3 expression in the TCGA and GEO databases, as well as in a glioma tissue microarray, and found that higher expression of STAT3 in tumour tissue predicted a poor prognosis." (PMID 36157880, 2022). "Our previous research established that IGFBP2 potentiates STAT3 transactivation activities by increasing nuclear EGFR amounts in glioma." (PMID 36556226, 2022). "Nevertheless, there has been limited discussion about how GSC antigens affect STAT3 expression in these imDCs and the immunological tolerance consequences of such perturbations in DC-induced T cells against glioma." (PMID 36157880, 2022). "S100B, a RAGE ligand that promotes tumorigenesis by promoting IL-6 expression and STAT-3 activation, is abundantly expressed in gliomas." (PMID 36613714, 2022). "One of the most common mutations in GBM, the deletion of exons 2–7 of the EGFR gene, called EGFRvIII, has been shown to activate Stat3 and Stat5 transcriptional pathways contributing to cell cycle progression and preventing apoptosis of glioma cells." (PMID 35625843, 2022). "At the same time, TMZ and DMC synergistically inactivate JAK/STAT3 signaling in human glioma cells, and this explains the significant suppression of cell proliferation and the apoptosis induction in a combined treatment." (PMID 35328780, 2022). "Analysis of glioma clinical biopsies confirmed a positive correlation between SOX9/STAT3/PML and poor patient survival among the cases with the highest SOX9 expression levels." (PMID 35562901, 2022).
glioma (continued). "In glioma, STAT3 is also overexpressed, and it is important for tumor cell cycle, tumor growth, and transformation as well as the angiogenesis." (PMID 36362294, 2022). "A recent study reported that Fraxetin inhibits proliferation and metastasis of glioma cells by inactivating JAK2/STAT3 signaling." (PMID 35387563, 2022). "Collectively, these results show that TMEM158-associated genes in gliomas are enriched in EMT and the STAT3 signaling pathway." (PMID 34992215, 2022). "SOCS3 is an inhibitor of STAT3 and the error of the SOCS3 regulation program on STAT3 leads to abnormal STAT3 expression in the brain tissue of glioma patients, which is due to phosphorylated STAT3 promoting the expression of many tumorigenesis genes." (PMID 35296090, 2022). "The majority of the antineoplastic activity of honeybee venom has been attributed to melittin through inhibition of VEGF, FLT-1, and MMP-9 in glioma C6 cells; metaloprotease-2 in human glioblastoma cells; and STAT3 and VEGF in glioma SHG44 cell." (PMID 39281062, 2022). "Taken together, these data endorsed the importance of tackling down STAT3 pathway in the battle of fighting glioma." (PMID 36618071, 2022). "They further revealed that B7-H3 induces glioma invasion through the JAK2/STAT3/Slug/MMP-2/-9 pathway and is involved in epithelial‐mesenchymal transition (EMT)." (PMID 36284349, 2022). "For example, ACYP2 was reported to contribute to the malignant progression of glioma by promoting Ca2+ efflux and the subsequent activation of c-Myc and STAT3 signals." (PMID 36147313, 2022). "As a result, the Macro index-high group was mainly transcriptionally regulated by NF-KB and STAT3, corroborating that STAT3 induces the immunosuppressive phenotype of glioma TAMs." (PMID 36159811, 2022). "miR-519a improves chemosensitivity and enhances autophagy in glioma by targeting STAT3/Bcl2 signaling." (PMID 35432536, 2022). "It has been demonstrated that aberrant activation of the STAT3 protein plays a critical role during glioma development and progression, such as promoting angiogenesis and immune escape of gliomas and glioma cell proliferation and differentiation." (PMID 35281458, 2022). "Activated STAT3 in glioma cells can also alter angiogenesis and GPTBE through the regulation of VEGF." (PMID 35741689, 2022). "The specific microRNA (miR-155) targets cytokine signaling suppressors, potentially leading to the overactivation of STAT3, a transcription factor important in glioma progression." (PMID 35626018, 2022). "Upregulated expression of signal transducer and activator of transcription 3 (STAT3) was found in glioma cell lines resistant to oxaliplatin." (PMID 35674307, 2022). "Here, we identified that the expression of STAT3 was repressed by the KAT6B knockdown in glioma cells." (PMID 35432536, 2022). "As previously reported, the IL6/JAK/STAT3 pathway was involved in the B7-H4(B7x)-mediated cross-talk between glioma-initiating cells and macrophages." (PMID 36233633, 2022). "For example, it has been reported that STAT3 contributes to tumor progression by promoting FOXP1 transcription in glioma." (PMID 35432536, 2022). "High DDR score gliomas exhibited the enrichment of multiple immune activation pathways including IL-6/JAK/STAT3 pathway, interferon-gamma response, inflammatory response, and antigen processing and presentation." (PMID 35720326, 2022). "Additional work has highlighted the role of macrophages in inducing mesenchymal-like state in glioblastoma, showing that macrophage-derived oncostatin M interacts with its receptor on glioma cells which in turn promotes mesenchymal state via STAT3 signaling." (PMID 35144680, 2022). "For example, under hypoxic conditions, glioma-derived exosomes can induce M2 macrophages polarization via the STAT3 pathway." (PMID 35410993, 2022). "Studies indicated that STAT3-mediated signaling played an important role in the resistance of glioma cells to oxaliplatin." (PMID 35674307, 2022).
glioma (continued). "The STAT3 signaling pathway is involved in a variety of cellular activities in glioma, including angiogenesis, invasion, chemotherapy resistance, and immune suppression." (PMID 34065991, 2021). "A 2018 study by Nathan B. Roberts suggested that oxaliplatin has powerful anticancer effects on malignant glioma cells by reprogramming the microenvironment, proposing that the main regulator of this process is STAT3." (PMID 34065991, 2021). "Among them, IL6 independently correlated with either age, prognosis, or the grade of the glioma, and activates STAT3, which is a reciprocally regulated cytokine network in tumor cells, including inflammation and angiogenesis factors such as IL-810." (PMID 34593910, 2021). "Collectively, LBX2-AS1 and miR-491-5p regulated the expression of N-cadherin, E-cadherin and Vimentin in glioma cells by the LIF/STAT3 axis." (PMID 34729101, 2021). "Transforming growth factor-β (TGF-β), which functions as an oncogene in glioma, can activate the Jak/Stat3 pathway in a Smad-dependent manner." (PMID 34425834, 2021). "Together, these results indicate that the tested STAT3 degrader SD‐36 possesses more potent activities than Stattic in inducing apoptosis of human glioma cells." (PMID 34291563, 2021). "One recently published study of STAT3 inhibition and radiation in a syngeneic immune-competent glioma mouse model found that the combination led to immunologic reprogramming of the TME, with increased dendritic cell–T cell interaction and antigen presentation." (PMID 33498872, 2021). "To further verify the inhibitory effect of fraxetin on the JAK2/STAT3 signaling pathway in glioma, we conducted experiments with the activator of JAK2/STAT3 pathway, Colivelin TFA." (PMID 33959183, 2021). "In glioma, ncRNAs can play an important role in upstream signals and mechanisms to regulate the expression and activation of STAT3." (PMID 34425834, 2021). "When glioma patients were considered according to their grade, intensity of p-STAT3 was confirmed to be an independent significant predictor of all grades of disease (accuracy of 68.6%)." (PMID 35069595, 2021). "By analysis with The Cancer Genome Atlas-Glioblastoma multiforme (TCGA-GBM) dataset, we found that UBE2D3 was highly expressed in glioma and it is positive correlation with glycolysis, apoptosis, and STAT3 pathway." (PMID 34195079, 2021). "These mast cells reduce the proliferative and invasive capacity of glioma cells and induce their differentiation by depleting the potency of glioma stem cells, possibly by inactivating the STAT3-mediated pathway through GSK3β downregulation." (PMID 34629960, 2021). "The result shows that CYB561D2 over-expressing glioma cells inhibited IL-2 secretion of mouse T cells in a STAT3-dependent manner." (PMID 34372858, 2021). "The results show that ascorbate promoted glioma cell proliferation and this effect was largely blocked by STAT3 inhibitor." (PMID 34372858, 2021). "MiR-124 can directly target STAT3 in glioma cells to inhibit their proliferation and promote cell apoptosis." (PMID 34425834, 2021). "GBM is characterized by abnormal activation of receptor tyrosine kinase signaling pathways, and constitutively activated STAT3 is frequently coexpressed with epidermal growth factor receptor (EGFR) in high-grade gliomas." (PMID 33980886, 2021). "While we did not observe any evident shift toward the mesenchymal cell state in our cells, STAT3 is known to promote tumor survival and proliferation and is a major driver of glioma cell migration and invasion." (PMID 34494550, 2021). "Plant/fruit-derived resveratrol, for instance, is capable of inhibiting proliferation and invasion of glioma cells in a STAT3-dependent fashion in vitro and when administered intrathecally in vivo." (PMID 33498872, 2021).
glioma (continued). "In normal cells, the activation of STAT3 is short-lived, while in glioma cells, STAT3 exhibits constitutively high activation and participates in the occurrence and development of tumours due to the lack of upstream regulatory signals." (PMID 34425834, 2021). "Activated STAT3 not only triggers glioma progression through affecting cell proliferation, apoptosis, invasion, and angiogenesis, but also functions as an inducer of immune evasion within GBM microenvironment." (PMID 34880206, 2021). "In a high percentage of GBM cells, persistent activation of STAT3 induces cell proliferation, anti-apoptosis, glioma stem cell maintenance, tumor invasion and immune evasion." (PMID 34257541, 2021). "For example, blocking the activity of IL-6R by tocilizumab (humanized antibody) in glioma cell line (U87MG) prevented cell proliferation through the JAK/STAT3 pathway." (PMID 34439380, 2021). "For example, EGFR and STAT3 were both highly expressed in gliomas and negatively correlated with the overall survival of gliomas." (PMID 34264013, 2021). "Of note, the inhibition of STAT-3 was observed in both glioma stem cells and differentiated glioma cells." (PMID 34944601, 2021). "This is in line with observations made in a glioma model where STAT3 inhibition enhanced CD45 + infiltration in tumors." (PMID 33786638, 2021). "In glioma stem cells, circATP5B competitively sponges miR-185-5p, upregulating the expression of the homeobox gene HOXB5, which induces the proliferation of glioma stem cells through JAK2/STAT3 signaling." (PMID 34439740, 2021). "In the STAT3 signalling pathway of glioma, miRNAs can directly target STAT3 mRNA, genes closely related to STAT3 activation (PIAS3, SOCS3), and upstream genes of STAT3." (PMID 34425834, 2021). "In summary, studies should investigate more circRNAs involved in the glioma STAT3 signalling pathway." (PMID 34425834, 2021). "For example, CASC9 (a kind of lncRNA), miR-519d, and STAT3 make a positive circle to activate glioma carcinomgenesis." (PMID 35052701, 2021). "Another study showed that circ-HIPK3 promotes the proliferation and invasion of glioma cells by acting as a sponge for miR-124-3p, resulting in the upregulation of signal transducer and activator of transcription 3 (STAT3)." (PMID 34112159, 2021). "STAT3 can induce the expression of Sox2 stimulating self-renewal capacity and stemness in glioma-derived CSCs." (PMID 34884812, 2021). "Other synthetic anti-inflammatory agents such as ibuprofen and diclofenac were found to reduce STAT3 phosphorylation in glioma cells." (PMID 34439380, 2021). "Interactions between microglia and glioma tumor cells can promote a mesenchymal cell state in glioma tumor cells, which is dependent on Stat3 activation." (PMID 34425907, 2021). "Previous studies have shown that B7-H3 overexpression can promote the occurrence of EMT in gliomas through the JAK2/STAT3/Slug signaling pathways." (PMID 34970415, 2021). "Overexpression of miR-29b can enhance the sensitivity of TMZ-resistant glioma cells to TMZ by inhibiting the expression of STAT3." (PMID 34425834, 2021). "Many studies have reported that STAT3 plays a key role in the occurrence and development of malignant tumors, especially gliomas." (PMID 34976781, 2021). "Our results suggested that fraxetin not only inhibits the proliferation, invasion, and migration of glioma but also induces glioma cells apoptosis by suppressing activation of JAK2/STAT3 signaling pathway." (PMID 33959183, 2021). "In this review, we summarized the ncRNAs that are correlated with the ectopic expression of STAT3 in glioma." (PMID 34425834, 2021). "The multi-faceted tumorigenic roles of STAT3 in human glioma cells has been well established by both molecular and pharmacologic inhibition." (PMID 33498872, 2021). "For example, in vivo and in vitro experiments have shown that c-myc, CCND1, Bcl-2, BCL-XL, Survivin, etc., are the direct target genes of STAT3 in the regulation of glioma cell proliferation." (PMID 34425834, 2021).